GSTT4 (glutathione S-transferase theta 4)
Description:
Conjugation of reduced glutathione to a wide number of exogenous and endogenous hydrophobic electrophiles.
Synonyms: GSTTP1; HS322B1A
Gene: Protein-coding gene on chromosome 22 (23,998,401 to 24,005,453, reverse strand). Ensembl gene ENSG00000276950.
Subcellular location: Cytoplasm
Gene Ontology:
Molecular function: glutathione transferase activity
Biological process: glutathione metabolic process
Cellular component: cytoplasm
Homologues: Orthologues: chimpanzee GSTT4 (92% identical), pig GSTT4 (78% identical), rabbit GSTT4 (75% identical), mouse Gstt4 (74% identical), guinea pig GSTT4 (72% identical), rat Gstt4 (72% identical), zebrafish gstt2 (35% identical), Drosophila melanogaster GstT1 (29% identical), Drosophila melanogaster GstT3 (28% identical), Drosophila melanogaster GstT2 (25% identical), Drosophila melanogaster GstE2 (22% identical), Drosophila melanogaster GstE4 (22% identical), and 36 more. Paralogues in human: GSTT2 (43% identical), GSTT2B (43% identical), EEF1G (22% identical), CLIC4 (20% identical), CLIC1 (19% identical), CLIC6 (19% identical), GDAP1 (18% identical), GDAP1L1 (18% identical), GSTO2 (18% identical), GSTO1 (17% identical), CLIC2 (17% identical), CLIC3 (17% identical), and 2 more.
Diseases named in the same sentence as GSTT4 in open-access papers:
GSTT4 is named in the same sentence as 7 diseases in open-access papers, as found by Europe PMC text mining. Sharing a sentence is not in itself a finding about the gene and the disease. The quoted sentences say what the papers report.
epilepsy (1 paper, 2023). A brain disorder characterized by episodes of abnormally increased neuronal discharge resulting in transient episodes of sensory or motor neurological dysfunction, or psychic dysfunction. "Finally, human orthologs of GSTT4 (hGSTT1 and hGSTT2) are implicated in cancer and epilepsy, which may be a result of increased oxidative stress in humans null, or otherwise mutant, for hGSTT1." (PMID 37578970, 2023).
meningioma (1 paper, 2024). A generally slow growing tumor attached to the dura mater. "Although none of 16 meningiomas displayed significant expression of GSTT4, nine tumors were GSTT4 hemizygous, while the rest were homozygous." (PMID 39726707, 2024). "Taken together with the fact that GSTT4 is not usually deleted in humans, these results suggest that GSTT4 hemizygous meningiomas lost a copy of the gene together with somatic deletion of chr22." (PMID 39726707, 2024).
GSTT4 also shares sentences with these, for which no sentence is quoted: breast tumours (1 paper); cancer (1); cervical cancer (1); ischemic stroke (1); tumours (1).